INS (insulin)
Diseases named in the same sentence as INS in open-access papers (continued):
Sharing a sentence is not in itself a finding about the gene and the disease.
hypertriglyceridemia (continued). "As a consequence of the increased release of free fatty acid (FFA) from adipose tissue to non-adipose tissue in an insulin resistance state, there is fatty acid accumulation in non-adipose tissues, such as liver, muscle, and heart, and hypertriglyceridemia." (PMID 36079745, 2022). "Hypertriglyceridemia contributes to a corresponding increase in free fatty acid (FFA) levels, which may impair insulin signaling and induce tissue oxidative stress, giving rise to IR in bone and liver." (PMID 36992743, 2022). "In hypertriglyceridemia, the TG and free fatty acids are deposited in nonadipose tissue, resulting in reduced insulin and IR biological effects." (PMID 34457002, 2021). "This combination stimulates liver very low-density lipoprotein (LDL) triglyceride (TG) secretion, leading to increased plasma TG concentrations and hypertriglyceridemia in insulin-resistant nondiabetic individuals." (PMID 34824593, 2021). "Patients with or without hypertriglyceridemia received homogeneous PN in terms of composition and insulin dose on the first day of nutrition support." (PMID 34371797, 2021). "In the newly diagnosed NS, hypertriglyceridemia has been a result of altered lipoprotein synthesis and metabolism, reflecting the severity of proteinuria rather than insulin resistance." (PMID 32795277, 2020). "An amelioration of biochemical parameters was also observed in response to the regionalized GENOMEX diet, as it significantly reduced the frequency of individuals with IR, hypertriglyceridemia, and increased VLDL-c, as well as it improved fasting glucose and insulin values." (PMID 32121184, 2020). "Women with vitamin D deficiency had a higher risk of developing MetS, hypertriglyceridemia and low HDL levels; other studies have shown negative effects on total cholesterol, triglycerides and insulin." (PMID 32946454, 2020). "There are many available therapies for hypertriglyceridemia-induced acute pancreatitis, including oral lipid-lowering agents, intravenous insulin with or without heparin, and plasmapheresis." (PMID 31215460, 2019). "Treatment with intravascular volume and electrolytes replacement as well as administration of intravenous insulin successfully resolved diabetic ketoacidosis (DKA) and hypertriglyceridemia (HTG) with a drop in triglyceride (TG) level from 1226 mg/dl to 193 mg/dl." (PMID 31431836, 2019). "Increased SUAC were significantly associated with higher waist-to-hip ratio (WHR), fasting insulin levels and insulin at 30 and 60 minutes during OGTT, HOMA-IR, lower HDL-c and presence of hypertriglyceridemia as well as with decreased HDL-c, increased AI, presence of IR and MetS." (PMID 30759960, 2019). "Fasting insulin values can be elevated, and sometimes accompanied by non-ketotic diabetes and hypertriglyceridemia." (PMID 29557732, 2018). "For biochemical measurements, obese children with/without hypertriglyceridemia also showed an increase in fasting insulin, HOMA-IR, TG, FFA and LDL-C, and concomitant reduction in HDL-C levels." (PMID 29895283, 2018). "In the absence of insulin, hypertriglyceridemia normatively occurs given that lipoprotein lipase (LpL) is not activated, an enzyme which is needed to hydrolyze TG." (PMID 29181401, 2017). "The postulated mechanism of hypertriglyceridemia in DKA patients centers on lack of insulin action, which activates lipolysis in adipose tissue that then results in free fatty acid (FFA) formation and increases in VLDL formation by the liver." (PMID 26904318, 2016). "There are no set established guidelines for the management of hypertriglyceridemia-induced pancreatitis, but the role of insulin, heparin, and plasmapheresis has been studied and successfully used in its management." (PMID 27785302, 2015). "Further, in diabetic state lipoprotein lipase is not initiated because of insulin inadequacy, stimulating hypertriglyceridemia." (PMID 25114914, 2014).
hypertriglyceridemia (continued). "In type 1 diabetic patients, the lipid profile observed along with the high blood glucose level includes hypertriglyceridemia and HDL lowness, which may be corrected by active insulin treatment." (PMID 25202704, 2014). "The optimal method of insulin administration (whether intravenous or subcutaneous) for managing hypertriglyceridemia remains undetermined due to a lack of comparative research." (PMID 39712682, 2024). "The ongoing Intensive Insulin Therapy vs. Plasmapheresis in the Management of Hypertriglyceridemia-Induced Acute Pancreatitis (Bi-TPAI) trial aims to evaluate whether intensive insulin therapy is non-inferior to plasmapheresis in patients with HTG-AP." (PMID 38543075, 2024). "The greater tendency of insulin resistance in non-LPL FCS may suggest a contribution of this secondary factor to severe hypertriglyceridaemia or the effect of non-LPL gene products in governing insulin sensitivity." (PMID 37233662, 2023). "Hypertriglyceridemia may result from the following several defects: (a) increased availability of non-esterified fatty acids to the liver due to insulin resistance and increased rates of lipolysis in the adipose tissue." (PMID 35683611, 2022). "In patients with T2DM and hypertriglyceridemia, pemafibrate also decreased other lipid components, namely non-HDL and remnant lipoprotein cholesterols, apolipoprotein (Apo) B100, ApoB48, ApoCIII while enhanced insulin sensitivity score, HDL-cholesterols, and ApoA-I levels in the blood circulation." (PMID 31614690, 2019). "Moreover, when we excluded the subjects being in the use of oral hypoglycemic, lipid-lowing agents and insulin, or with severe hypertriglyceridemia, the ROC values did not appreciably alter compared to the analyses that included these participants." (PMID 29158535, 2017). "Of note, the E167K variant in TM6SF2 is associated with a distinct subtype of NAFLD, characterized by preserved insulin sensitivity with regard to lipolysis, hepatic glucose production, and lack of hypertriglyceridemia despite a clearly increased liver fat content." (PMID 26273598, 2015). "Consequently, the lack of changes in insulin concentration during fructose intake does not affect lipoprotein lipase activity, which may lead to hypertriglyceridemia." (PMID 31684199, 2019). "However, it has been reported that high-carbohydrate diets can induce hypertriglyceridemia, possibly by slowing the removal of triacylglycerols (chylomicrons) from the blood or by increasing hepatic VLDL release (as reported in a study of insulin-resistant subjects)." (PMID 26333512, 2015). "Under normal conditions, insulin activates the enzyme lipoprotein lipase (LPL), but if insulin is not present, LPL is not activated, resulting in hyperglyceridemia and hypercholesterolemia." (PMID 29048380, 2017). "Normally, insulin stimulates lipoprotein lipase (LPL; an enzyme that catalyzes the hydrolysis of TG) activity, but in the absence of insulin, LPL cannot be activated, leading to hyperglyceridemia and hypercholesterolemia." (PMID 38629096, 2024).
coronary artery disease (484 papers, 2006 to 2026). "Ischemic heart disease, foot skin changes, insulin use, and low hemoglobin were associated factors of DFU risk." (PMID 42037920, 2026). "Based on a study with coronary disease patients, the adipocyte hypertrophy of EF was significantly associated to increased fasting glucose and decreased insulin levels." (PMID 37857994, 2024). "Plasma betaine has been inversely associated with fasting glucose and HbA1c in coronary artery disease patients and with greater insulin sensitivity in the CHS." (PMID 38612993, 2024). "A previous study observed that diets rich in sugar can lead to abnormalities associated with increased coronary heart disease, including leptin resistance, high levels of glucose, insulin, and uric acid." (PMID 38140309, 2023). "The third co-citation article, published in 1996, identified fasting insulin concentration as an independent risk factor for ischemic heart disease through a prospective cohort study of Canadian men." (PMID 36950100, 2023). "Due to the unrestricted effects of lipolytic hormones on fat deposits, primarily as a result of the action of insulin, which is a risk factor for coronary heart disease, the levels of serum lipids are typically high in DM." (PMID 36624877, 2022). "The analysis shows that HbA1C variability was associated with insulin usage (OR = 4.1, p < 0.001), younger age (OR = 0.939, p < 0.001) and Ischemic heart disease (OR = 1.258, p = 0.03)." (PMID 34537062, 2021). "The multivariate analysis showed that HbA1C variability was associated with insulin use (OR = 4.1, p < 0.001), with age (OR = 0.939, p < 0.001), and Ischemic heart disease (OR = 1.258, p = 0.03)." (PMID 34537062, 2021). "In the multivariate analysis we found an association between HbA1C variability, insulin use, and ischemic heart disease, both are markers of a more challenging disease, which supports this assumption." (PMID 34537062, 2021). "Previously, it was reported that increased insulin and C-peptide levels were independently associated with increased risk of coronary artery disease in T2DM subjects." (PMID 30674322, 2019). "In BARI-2D trial, the researchers have shown that insulin, and its secretagogues are more likely to cause an increased prevalence of albuminuria and coronary artery disease, compared to insulin-sensitizing drugs." (PMID 30799525, 2019). "Low education level, rural residence, unhealthy eating habits, insulin use, infrequent follow up check-ups and history of coronary artery diseases found associated with inadequate and very poor controls." (PMID 31308457, 2019). "Genetically predicted insulin, i.e., insulin proxied by genetic variants, is positively associated with ischemic heart disease, but sex differences are unclear, despite different disease rates and reproductive strategies by sex." (PMID 31508506, 2019). "Earlier studies have also reported that the altered methylation of guanine nucleotide-binding protein G(s) subunit alpha isoforms short (GNASAS) and insulin (INS) is associated with the increased risk of developing coronary heart disease." (PMID 29062799, 2017). "Low adiponectin concentrations which has been previously associated with coronary artery disease in the adult population of Guadeloupe correlated with high plasma insulin levels and adverse blood lipid profile in the present study in children." (PMID 26581745, 2015). "These variables are: high-risk type of surgery, history of ischemic heart disease, history of congestive heart failure, history of cerebrovascular disease, preoperative treatment with insulin, and preoperative serum creatinine 2.0 mg/dl." (PMID 24791166, 2014). "Similarly, epicardial adipose tissue, which increases with BMI, is associated with elevated fasting insulin, higher diastolic blood pressure, and coronary artery disease." (PMID 40600774, 2025).
coronary artery disease (continued). "If sustained over time, the improvements in the ΔGLU and GLUpeak after the MM may facilitate improvements in β-cell function, improve insulin sensitivity and lipid metabolism, and decrease the risk of developing coronary heart disease." (PMID 41465023, 2025). "In patients with T2DM with underlying ischemic heart disease who were receiving metformin and insulin therapy, endothelial function in the group of patients with T2DM with an HbA1c > 7.0% at baseline was improved by additional therapy with dapagliflozin for 12 weeks compared to placebo." (PMID 39338292, 2024). "In addition, baseline levels of insulin have been associated with atherogenic progression and coronary artery disease incidence in population-based cohort studies." (PMID 37175639, 2023). "There is substantial scientific evidence that high consumption of flavonols is associated with reduced risk of cancer and coronary diseases, free radical damage alleviation, tumor growth prevention, and insulin secretion improvement, among other diverse health benefits." (PMID 37216013, 2023). "Impaired insulin sensitivity may contribute to occlusive vascular disease, which has been positively related to increased risk of coronary artery disease and ischemic stroke in the general population." (PMID 36355827, 2022). "Indeed, consistently with prior reports, our analysis found that the prevalence of renal disease, peripheral, cerebrovascular and coronary artery disease, and insulin use are associated at baseline with longer DM duration." (PMID 36309742, 2022). "Likewise, the associations have been observed between polymorphisms in FADS genes and high D6D activity, as well as between these variants and increased levels of inflammatory markers and fasting insulin and a higher risk of coronary artery disease." (PMID 34164423, 2021). "The objective of this study was to examine the relationship of fasting glucose (FBG), insulin and C-peptide to the long-term risk for incident coronary heart disease in elderly Japanese-American men who were 61–81 years of age at the baseline exam in 1980–1982." (PMID 30555835, 2018). "This index takes into account the following: high-risk surgical procedures, history of ischemic heart disease, history of congestive heart failure, history of cerebrovascular disease, DM requiring insulin treatment, and preoperative serum creatinine of >2.0 mg/dL (177 μmol/L)." (PMID 30271785, 2018). "Coronary artery disease is significantly associated with fasting insulin levels." (PMID 26758313, 2016). "In a model comprising age, sex, smoking habits, BMI, HbA1c, and insulin, antihypertensive and antidyslipidemic therapies, serum resistin was associated with coronary artery disease in both cross-sectional studies: OR (95%CI) per SD increment = 1.35 (1.10–1.64) and 1.99 (1.55–2.55)." (PMID 23755138, 2014). "Fleisher and Eagle summarized six predictive factors of perioperative increased cardiac risk including ischemic heart disease, heart failure, high risk surgery (intraperitoneal, intrathoracic, vascular), diabetes mellitus requiring insulin, renal failure, and poor functional capacity." (PMID 24791166, 2014). "Further studies will help to determine whether cocoa tea is of therapeutic benefit in patients with NAFLD or in overweight and insulin-resistant individuals at increased risk of coronary artery disease." (PMID 23935682, 2013). "Potentially, sufficient amounts of LA in the serum or diet could improve insulin sensitivity and reduce coronary heart disease risk or mortality." (PMID 23383292, 2013). "Improvements in whole-body insulin sensitivity and glycemic control are closely associated with attenuation of cardiac insulin resistance and appear to protect the heart in both patients and animals with coronary heart disease." (PMID 21080957, 2010).
coronary artery disease (continued). "Our findings have shown that the insulin+secretagogue based therapy group was statistically associated with risk factors including disease duration and age, having higher proportion of patients with coronary heart disease, peripheral artery disease and osteoporosis." (PMID 33402217, 2021). "Finally, the higher incidence of comorbidities, such as coronary artery disease and impaired renal function, could possibly contribute to the increased mortality risk in patients treated with insulin." (PMID 31138207, 2019). "The improved fitness both immediately and one year after the intervention may have both psychosocial and other health related effects, such as improved lipid profile, insulin sensitivity, decreased blood pressure and reduced coronary heart disease risk later in life." (PMID 23547765, 2013). "Other comorbidities mainly included Obstructive Sleep Apnea (n = 2), Chronic Obstructive Pulmonary Disease (n = 2), ischemic heart disease (n = 2), hypercholesterolemia (n = 1), serous otitis media (n = 1), insulin resistance (n = 1), and glaucoma (n = 1)." (PMID 39997294, 2025). "Consistent with these recommendations, our study showed that in insulin-treated patients with T2D, GLP-1 RA use significantly reduced the risk of hospitalization for coronary artery disease compared with DPP-4 inhibitor and sulfonylurea use." (PMID 41011236, 2025). "We found a mediating role for insulin in the associations of TyG with total CVD, congestive heart failure, and angina pectoris and TyG-BMI with total CVD and coronary heart disease." (PMID 38184598, 2024). "Another study which was a retrospective study with patients with coronary artery disease undergoing PCI, enrolled from 2009 to 2018, patients with DM had a higher disease risk profile, especially those on insulin therapy." (PMID 38504170, 2024). "Patients with ischemic heart disease and normal left ventricular function were found to be insulin resistant and hyperinsulinemic but to a significantly lesser degree than patients with chronic HF due to ischemic heart disease." (PMID 39342254, 2024). "In conclusion, the results of our study underscore the relationships between age, cholesterol, triglyceride, ischemic heart disease, insulin, OADs, and OADs plus insulin with HbA1c levels across different quantiles." (PMID 37308493, 2023). "Similar to the use of DES, the need for insulin in the setting of de novo coronary artery disease in small vessels in diabetic patients treated with DCB is associated with higher adverse events compared to NITDM patients." (PMID 36975883, 2023). "Replacing dietary SFA with PUFA has been reported to lower coronary heart disease events and improve glycemic control, insulin resistance, and insulin secretion capacity." (PMID 37375568, 2023). "Add‐on DPP‐4i therapy would be beneficial in preventing coronary artery disease progression in patients with T2DM receiving insulin therapy." (PMID 37528628, 2023). "Cholesterol, triglyceride, ischemic heart disease (IHD), insulin, OADs, and the combination of OADs plus insulin demonstrated significant associations across all quantiles (p < 0.001)." (PMID 37308493, 2023). "Glucose-insulin-potassium (GIK) regimen in patients with ischemic heart disease (acute myocardial infarction) or IBD has been found to inhibit inflammatory processes and appear to be cytoprotective." (PMID 37063831, 2023). "The top 10 keywords for centrality were “glycation end product,” “diagnosis,” “neuropathy,” “insulin,” “follow up,” “diabetic nephropathy,” “oxidative stress,” insulin resistance,” “glomerular filtration rate,” and “coronary heart disease”." (PMID 35795563, 2022). "Favorable effects were also observed across all age groups, including ≥ 75 years, in patients with coronary artery disease or atrial fibrillation and with concomitant β-blocker, diuretics, or insulin." (PMID 35964039, 2022).